IL2 (interleukin 2)
Diseases named in the same sentence as IL2 in open-access papers (continued):
Sharing a sentence is not in itself a finding about the gene and the disease.
rheumatoid arthritis (continued). "For example, in rheumatoid arthritis TNF-β levels in the synovium are elevated, as are serum levels of IL-2." (PMID 26192591, 2015). "Thus, we obtained peripheral blood from healthy donors and rheumatoid arthritis patients, and CD4+ T lymphocytes were purified and cultured for 5 days in the presence of anti-CD3/CD28 beads and recombinant interleukin-2 (IL-2)." (PMID 36902005, 2023). "In our previous report, we found that serum BDNF was elevated in patients with rheumatoid arthritis and BDNF could promote IL-2, IL-17, and IFN-γ expression in Jurkat cells." (PMID 35009001, 2022). "Moreover, it has been documented that over-expression of miR-99b-5p brings about elevations in the expression levels of proinflammatory cytokines (IL-2, IL-6, TNFα, and IFN-γ), thus promoting the pathogenesis of rheumatoid arthritis." (PMID 33109608, 2020). "CTLA-4-Ig, an IgG Fc fusion homodimer of the extracellular domain of CTLA-4, which is currently approved therapeutic agent for rheumatoid arthritis, substantially inhibited IL-2 secretion from Jurkat cells, regardless of RGMB expression levels." (PMID 31061392, 2019). "In patients with OA, the immunoexpression levels of TNF-α, IL-1β, IL-7, MMP-1, MMP-2, and MMP-3 were significantly higher in patients with active rheumatoid arthritis (RA), whereas the immunoexpression levels of IL-1, IL-2, IL-4, IL-6, IL-15, IL-18, and MMP-3 were not statistically different." (PMID 40004793, 2025).
malaria (84 papers, 2008 to 2026). Malaria is a serious and sometimes fatal disease caused by a parasite that commonly infects a certain type of mosquito which feeds on humans. "This systematic review and meta-analysis aimed to synthesize available evidence on IL-2 levels in malaria patients and assess their association with disease severity." (PMID 41194029, 2025). "As a result, it is imperative to establish a more comprehensive understanding of IL-2’s function in varying clinical outcomes associated with malaria." (PMID 41194029, 2025). "Enhanced frequencies of IFNγ-secreting NK cells upon malaria vaccination were associated with antigen-specific IL-2 secretion and considered as a marker for antigen-specific T cell activation." (PMID 32517137, 2020). "CD4+ T cells producing other cytokines such IL-2, IL-10 and IL-4 alone or in combination with the studied cytokines have been shown to be associated with protection from malaria." (PMID 27165269, 2016). "Multinominal regression analyses adjusted for age and gender revealed that severe malaria was associated with higher levels of IL-2 (p = 0.025) and IL-13 (p = 0.018) than malaria with hyperbilirubinaemia." (PMID 26466783, 2015). "The main effects (i.e. without considering an interaction) of IFNγ-IL2+TNF−, IFNγ-IL2+TNF+, and IFNγ-IL2-TNF+ CD4+ T cells were reductions in the risk of clinical malaria of varying statistical significance." (PMID 23300801, 2012). "Interleukin-2 (IL-2), a pro-inflammatory cytokine implicated in malaria pathogenesis has also been shown to be a key regulator of Foxp3." (PMID 21439091, 2011). "Additionally, some of the included studies were cross-sectional in design, which limits the ability to assess temporal and causal relationships between IL-2 levels and malaria severity." (PMID 41194029, 2025). "Severe malaria was also associated with higher levels of IL-1β (p = 0.008), IL-2 (p = 0.001), IL-4 (p = 0.041), IL-12p70 (p = 0.010), IL-13 (p = 0.004), IFN-γ (p = 0.041), TNF (p = 0.049), IFN-γ/IL-10 (p = 0.016), TNF/IL-10 (p = 0.016) and (TNF + IFN-γ)/IL-10 (p = 0.001) than mild malaria." (PMID 26466783, 2015). "Although IFN-γ has been associated with malaria protection and IL-2 may be key for the generation of effector responses to malaria, the strong TH1 and inflammatory responses detected reflect innate rather than protective adaptive immune responses." (PMID 23437061, 2013). "It has been also shown that cytokines play an important role in the immunopathology of malaria and many field studies have described an association of specific cytokines with severity of disease, in particular IL-2, IL-12, IFN-γ, IL-1β, IL-6, TNF, IL-4, IL-10, MIP-1β, and TGF-β." (PMID 22280502, 2012). "All these T cells phenotypes were individually associated with reductions in the risk of clinical malaria, but IFNγ-IL2-TNF+ CD4+ T cells independently predicted reduced risk of clinical malaria on multi-variable analysis (HR = 0.29, 95% confidence intervals 0.15–0.54, p<0.0005)." (PMID 23300801, 2012). "However, IFNγ-IL2-TNF+ CD4+ T cells were independently associated with protection against clinical malaria, and were induced by natural exposure." (PMID 23300801, 2012). "Our co-culture system may well reflect the processes occurring in vivo during malaria-infection, and explain the elevated levels of CD4+CD25hiFoxp3+ T cells observed in malaria-infected individuals and the association of IL-10, TGFβ and IL-2 with their induction." (PMID 19680449, 2009). "For the different continents, studies conducted in Africa and Asia showed a similar trend, with IL-2 levels being higher in malaria patients compared to uninfected individuals." (PMID 41194029, 2025). "This systematic review and meta-analysis aim to address this gap by examining the differences in IL-2 levels among patients with differing malaria severity, including uncomplicated cases, compared to a control group of healthy individuals." (PMID 41194029, 2025).
malaria (continued). "Studies have highlighted IL-2’s significant role in malaria pathogenesis, as evidenced by elevated levels during Plasmodium infection." (PMID 41194029, 2025). "While only two studies (n = 2, 8.7%) reported a significant decrease in IL-2 levels in malaria patients compared to uninfected individuals." (PMID 41194029, 2025). "Future research should aim to expand on the present findings by incorporating a larger dataset of IL-2 measurements, providing a more comprehensive understanding of the role of IL-2 in malaria." (PMID 41194029, 2025). "Aside from the significant difference in IL-2 level recorded in all patient groups, there was significant difference between typhoid group and typho-malaria group (p = 0.0215)." (PMID 40014608, 2025). "Among the patient groups, the mean IL-2/IL-10 ratio was significantly higher in typho-malaria group compared to the malaria group (p = 0.0067)." (PMID 40014608, 2025). "In the malaria and typhoid fever co-morbidity group, a positive correlation was recoded between IL-2/TNFα (r = 0.515, p = 0.03), IL-2/IL-6 (r = 0.536, p = 0.02) and IL-6/TNF-α (r = 0.664, p = 0.007)." (PMID 40014608, 2025). "Six studies provided data for a meta-analysis comparing IL-2 levels between patients with malaria (n = 629) and uninfected individuals (n = 445)." (PMID 41194029, 2025). "Regarding continent and country, studies from South America reported increased IL-2 levels in severe malaria, while those from Asia and Europe reported decreased IL-2 levels in severe malaria." (PMID 41194029, 2025). "That notwithstanding, some studies (n = 8, 34.8%) found a significant increase in IL-2 levels in malaria patients compared to uninfected individuals." (PMID 41194029, 2025). "Studies were eligible if they reported IL-2 levels in human participants with malaria, compared to uninfected individuals, and/or across malaria severity." (PMID 41194029, 2025). "The IL-2 response to Plasmodium infection appears to be largely unaffected by age, aligning with previous research on age-related immune responses in malaria." (PMID 41194029, 2025). "While cytokines such as IL-6 and tumor necrosis factor-α (TNF-α) have been extensively studied in malaria pathogenesis, the role of IL-2 remains poorly understood and inconsistently reported across studies." (PMID 41194029, 2025). "While TNF levels were significantly increased in the coinfection group, IL-2 levels were significantly decreased compared to the malaria monoinfection group in two studies." (PMID 36716305, 2023). "IL-2 and IL-5 levels were observed as either lower or higher in malaria coinfections compared to intestinal parasite monoinfection." (PMID 36716305, 2023). "A subunit malaria vaccine confers protection against sporozoite challenge by increasing the production of IL-2-secreting CD4+T cells." (PMID 36504817, 2022). "The ex vivo FluoroSpot assay was used to measure peripheral IFN-γ, IL2, and IFN-γ+IL2 responses to PfNF54 sporozoites and malaria antigens CSP, AMA1, TRAP, and CelTOS using pools of synthetic overlapping 15mer peptides spanning each antigen." (PMID 34415964, 2021). "Relative researches found that the maintenance of CD25+Foxp3+ cells required IL-2 assist critically in malaria." (PMID 32252652, 2020). "Previous work has shown that IL-2 produced by T cells following malaria infection or injection of a malaria vaccine activates IFN-γ production by NK cells." (PMID 29943728, 2018). "Surprisingly, non-Vγ9 γδ T cells from NCs and UMPs in the malaria-endemic area increased 10-fold in the presence of IL-2 or IL-2 and Pf Ag after 10 days of culture." (PMID 28769886, 2017). "The majority of triple-positive (81.7%) were IFN-γ+TNF-α+IL2+-expressing at the time of an acute malaria episode." (PMID 29449839, 2017). "Subsequent studies have demonstrated a similar IL-2-dependent effect in response to malaria-infected erythrocytes." (PMID 28337195, 2017).
malaria (continued). "IL-2 levels in convalescence in all malaria types were similar to those of controls (medians, 1.60 pg/ml for UCM, 1.30 pg/ml for SMA, 1.65 pg/ml for CM)." (PMID 28122790, 2017). "We used crude Pf Ag when culturing PBMCs from people living in malaria-endemic area, but the γδT cell response to crude Pf Ag in the presence of IL-2 was slightly different from that in the presence of IL-2 alone." (PMID 28769886, 2017). "The majority of triple-positive [10.5/11.9 (88.2%)] were IFN-γ+TNFα+IL2+-expressing at the time of an acute malaria episode." (PMID 29449839, 2017). "The data analysis demonstrated that both malaria groups have significantly increased levels of IL-2, IL-4, IL-6, IL-10, TNF and IFN-γ as compared to the endemic controls." (PMID 27581163, 2016). "Polyfunctional T cells co-producing IFN-γ, TNF-α and IL-2 are associated with infection control in HIV, hepatitis C, leishmaniasis and malaria." (PMID 25879774, 2015). "Subjects with severe malaria had higher levels of interleukin (IL)-2 and IL-13 than subjects with hyperbilirubinaemia." (PMID 26466783, 2015). "Malaria-specific production of IL-2 was tested in a subset of children (n = 44), but responses were consistently of low magnitude (median frequency 0.02%, data not shown)." (PMID 24415936, 2014). "Immigrants had higher levels of IL-2, IL-5 and IL-8 compared to semi-immune adults with malaria (P≤0.0200)." (PMID 23967342, 2013). "There was an association between the frequency of RTS,S/AS01E induced CSP-specific CD4+ T cells and protection from clinical malaria, most strongly seen for IFNγ-IL2-TNF+ CD4+ T cells." (PMID 23300801, 2012). "We also show that IFNγ-IL2+TNF−, IFNγ-IL2+TNF+, and IFNγ-IL2-TNF+ CD4+ T cells were induced by natural exposure to malaria in the control vaccinees." (PMID 23300801, 2012). "After PBMC from wet season samples were depleted of CD25hi cells and stimulated with pooled malaria antigen, increased IL-2 and IFN-γ expression was noted in 27–43% of experiments compared to the mock-depleted cells." (PMID 22348117, 2012). "Similar observations have been reported where malaria patients responded to P. falciparum infected erythrocytes with significant increases in the percentage of IL-2, IFN-γ, and TNF, but also IL-10, positive cells." (PMID 22280502, 2012). "Future in vivo studies in populations affected with malaria should explore the significance of IL-2 on the production of IFNγ at early stages of infection and in subjects with different degree of previous exposure to malarial antigens." (PMID 22316273, 2012). "It has been suggested that IL-2 and IFN-γ producing T cells after vaccination of adults are associated with the induction of memory T cell responses to pre-erythrocytic malaria antigens." (PMID 21494604, 2011). "By contrast, malaria antigen with IL-2+IL-15 augmented four of 21 (19%) in the exposed sensitized group and two of 17 (11%) in the not-exposed children." (PMID 19636353, 2009). "Exposed not sensitized children also had 2- to 3-fold lower frequency of malaria antigen-driven IFNγ and/or IL-2 production (p<0.001) and higher IL-10 release (p<0.001) at 6-month follow-ups, when compared to sensitized and not-exposed children." (PMID 19636353, 2009). "These impaired antigen-specific Th1-type responses in putatively tolerant children were malaria-specific, since tetanus toxoid (TT)-driven IFNγ, IL-2, and/or lymphocyte proliferation responses were comparable between the three groups." (PMID 19636353, 2009). "Exposed not sensitized children had evidence for prenatal immune experience demonstrated by increased IL-10 production and partial reversal of malaria antigen-specific hyporesponsiveness with IL-2+IL-15, indicative of immune tolerance." (PMID 19636353, 2009).
malaria (continued). "For instance, in severe malaria, elevated levels of IFN-γ and TNF-α, along with the upregulation of TGF-β mRNA, have been shown to cause downregulation of IL-12α and IL-2 levels, suggesting potential dysregulation of the cytokine network through T cell suppression." (PMID 41194029, 2025). "Supporting this complexity, a recent study found that areas with high transmission intensity exhibited decreased pro-inflammatory cytokine responses, including IL-2, during acute malaria, suggesting that repeated exposure may impact cytokine levels." (PMID 41194029, 2025). "IL-2 is a key cytokine involved in the activation and proliferation of T-cells, which are central to the adaptive immune response against pathogens including malaria parasites." (PMID 41194029, 2025). "Given the unique immunological challenges posed by Plasmodium species, the role of IL-2 in malaria may differ from its function in other infections." (PMID 41194029, 2025). "While cytokines such as IL-6, IL-1β, and TNF-α have been extensively studied in relation to malaria severity, the role of IL-2 in immune regulation, T cell activation, and its potential dual contributions to both protective and pathogenic responses remain less well understood." (PMID 41194029, 2025). "Notably, cytokine levels were elevated in patients with malaria and typhoid comorbidity, particularly IL-1β, IL-2, TNF-α, and IFN-γ." (PMID 40014608, 2025). "This implies that cytokine responses, including IL-2 levels, in malaria patients may be affected by factors beyond age, such as the frequency of exposure to clinical malaria." (PMID 41194029, 2025). "Insights gained from this study may help guide the development of diagnostic methods or therapeutic strategies aimed at modulating IL-2 levels to improve patient outcomes in malaria." (PMID 41194029, 2025). "Given the high variability in the analyses, further well-designed studies are needed to explore whether IL-2, in combination with other immunological biomarkers, could serve as a reliable indicator for Plasmodium infections and severe malaria." (PMID 41194029, 2025). "Specifically, IL-2, a cytokine required for regulatory T cell expansion in malaria, was increased compared with baseline at day 4 PI, and this pattern persisted through day 10 PI in basoIL-18R (−) mice, while basoIL-18R (+) mice showed an increase above baseline only at days 6 and 8 PI." (PMID 35985797, 2022). "CD4 and CD8 T cells producing IFNg, interleukin 2 (IL2) and tumor necrosis factor alpha (TNFa) were detected in peripheral blood after immunization of malaria naïve volunteers, however, their levels rapidly declined over time and were not correlated with protection." (PMID 32662772, 2020). "Also, it has been shown that the levels of TNF-α, IL-2, IL-10, IL-6 in Plasmodium-helminth co-infected individuals were significantly higher than the malaria-positive (MP) group dampening the immune response to malaria." (PMID 33170876, 2020). "A fusion protein consisting of a protein called cell-traversal protein for ookinetes and sporozoites (CelTOS) antigen from Plasmodium falciparum (the deadliest of malaria species) and human IL-2 as an adjuvant was designed to develop a candidate vaccine against malaria." (PMID 28491487, 2017). "Indeed, only in the younger age group were TNF, IL6, and IL2 concentrations elevated during acute malaria (day 0) as compared to convalescence (week 3)." (PMID 29284469, 2017). "Notably, enhanced IFN-γ production by NK cells from individuals experimentally infected with malaria up to 20 weeks after initial infection appears to be dependent on the presence of both IL-2 and T cells." (PMID 28337195, 2017). "Although inflammatory responses, including interferon gamma (IFN-γ), IL-12, IL-1β, IL-2, and TNF-α, play important roles that facilitate parasite clearance, circulating high levels of these cytokines have been associated with malaria immunopathology." (PMID 28399920, 2017).